NOTCH1 (notch receptor 1)
Diseases named in the same sentence as NOTCH1 in open-access papers (continued):
Sharing a sentence is not in itself a finding about the gene and the disease.
ovarian carcinoma (continued). "Importantly, inhibition of Notch1 signaling by overexpression of miR-449a could sensitize chemoresistant ovarian cancer cells to cisplatin-induced cytotoxicity." (PMID 29104587, 2017). "In addition, CSC-enriched spheres from different ovarian cancer cells showed increased expression of NOTCH1, and inhibition of NOTCH signaling with DAPT resulted in loss of CSC characteristics, whereas NICD1 overexpression led to acquisition of CSC characteristics." (PMID 27489349, 2016). "Additionally, Cav-1 could promote the chemoresistance of ovarian cancer by targeting apoptosis through the Notch1/Akt/NF-κB pathway." (PMID 27184229, 2016). "Therefore, we strongly suggest that galectin-3 may be a potent target for regulating Notch1 signaling in ovarian cancer therapeutic strategies." (PMID 27626163, 2016). "Hence, we speculated that JAG1-mediated Notch1 signaling activity is involved in ovarian cancer oncogenesis and chemoresistance." (PMID 24659709, 2014). "In glioblastoma and ovarian cancer, KLF9 was shown to repress the expression of the Notch 1 gene, thereby resulting in reversion away from the stem cell phenotype due to less active Notch signaling." (PMID 38067370, 2023). "After XH therapy, significant growth inhibition and downregulation of protein expression and Notch1 transcription were discovered in SKOV3 and OVCAR3 ovarian cancer cells." (PMID 33923053, 2021). "Blocking of the Notch1 activity by inhibiting gamma-secretase is unable to release Notch intracellular domain (NICD), which retards ovarian tumor growth and induces ovarian cancer cell apoptosis." (PMID 34277625, 2021). "In ovarian cancer, HIF-1α activates Notch1 signaling, which increases the activity of the Sox2 promoter, creating a CSC phenotype and drives drug resistance in ovarian cancer stem cells." (PMID 34867818, 2021). "The activation of NOTCH1, one of four main NOTCH receptors, drives the metastasis of ovarian carcinoma cells and the resistance of OCSCs." (PMID 33224949, 2020). "For the first time, our study examined the effects of LGR5 on the biological behavior of epithelial ovarian cancer and explored the relationship between LGR5 and Notch1 pathway in epithelial ovarian cancer." (PMID 29777575, 2018). "Therefore, we confirmed whether Notch1 received processing by Furin in ovarian cancer cells." (PMID 29423060, 2018). "Thus Notch1 and Notch2 might be potential drug targets for some types of ovarian cancer patients." (PMID 28415574, 2017). "Additionally, CCL20 promotes ovarian cancer resistance by modulating ABCB1 expression and Notch1 signaling pathway." (PMID 40968783, 2026). "We found NOTCH1 among the top 20 hub genes in endothelial CGNs for all four cancer types (7th for breast, 13th for colorectal, 11th for lung and 19th for ovarian cancers), but not among the top 200 DEGs in all cancer types." (PMID 36350625, 2023). "It has been reported that Notch1 induces Snail expression in immortalized endothelial cells in vitro and that overexpression of NICD1 inhibits E-cadherin expression and induces EMT in ovarian cancer cells." (PMID 30034624, 2018). "The expressions of Notch1, Jagged1 and NICD in Notch1 pathway did not correlate with outcome in ovarian cancer." (PMID 28030808, 2017). "Notch1 mRNA high expression was not correlated to OS for all ovarian cancer patients followed for 20 years, HR 0.89 (0.78–1.02), p = 0.1." (PMID 28415574, 2017). "In this study, we found that Notch1 mRNA high expression was not correlated to PFS for all ovarian cancer patients." (PMID 28415574, 2017). "Notch1 mRNA high expression was also not correlated to PFS ovarian cancer patients, 0.93 (0.81–1.06), p = 0.27, as well as PPS in ovarian cancer patients, HR 1.17 (0.98–1.4), p = 0.081." (PMID 28415574, 2017).
ovarian carcinoma (continued). "In the current study, we explored the roles of hypoxia, NOTCH1, and SOX2 in the sphere-forming ability, drug resistance, and CSC marker expression of CSC-like cells isolated from ovarian cancer cell lines and primary ovarian cancer cells." (PMID 27489349, 2016). "XN has shown to reduce Notch1 expression in ovarian cancer cells but the mechanistic action of XN is not clear." (PMID 26011160, 2015). "A recent study has suggested that the modulation of tumor angiogenesis by blocking VEGF signaling could reduce the chemoresistance of ovarian cancer, suggesting that JAG1/NOTCH1/neovascularization confers ovarian cancer chemoresistance." (PMID 24659709, 2014). "By contrast, little or no NOTCH1 activation was observed in mantle cell lymphoma, diffuse large B cell lymphoma, non-small cell lung cancers, and ovarian carcinoma." (PMID 23825651, 2013). "Notably, Notch1 signaling enables CSCs to migrate and invade, even under normoxic conditions, which typically do not favor metastasis, as observed in ovarian cancer, highlighting the pro-metastatic role of Notch1 in CSCs." (PMID 40430852, 2025). "Finally, variants in the genes ROS1, NOTCH1, ALK, KMT2D, and SPOP have to our knowledge not previously been reported in ovarian cancer." (PMID 28611940, 2017). "In addition, Notch1 mRNA high expression was also not correlated to PFS ovarian cancer patients, 0.93 (0.81–1.06), p = 0.27, as well as PPS in ovarian cancer patients, HR 1.17 (0.98–1.4), p = 0.081." (PMID 28415574, 2017). "However, whether Notch1 regulates EMT to induce chemo-resistance ovarian cancer has not been reported." (PMID 32547317, 2020). "The results presented that the expressions of Notch1, Jagged1 and NICD in ovarian cancers were not correlated with age, family history, ascites, serum CA125, size of tumour, FIGO stage, differentiation and pathology (P > 0.05)." (PMID 28030808, 2017). "In this research, we found the expressions of Notch1, Jagged1 and NICD in ovarian cancers were not correlated with clinicopathologic factors, which needs more specimens to be demonstrated." (PMID 28030808, 2017). "In contrast to the findings of the full-length Notch1 IHC studies, NICD1 was not expressed in any of the 147 analyzed ovarian cancer specimens although a subset of samples from other cancer types showed nuclear NICD1 immunostaining with this method." (PMID 25366565, 2014). "Over-expression of NOTCH1 intracellular domain, but not HES1 or HEY1, inhibits E-cadherin expression and induces EMT in ovarian cancer cells, probably through the induction of Snail expression." (PMID 20010940, 2010). "In addition, NOTCH1 signaling may mediate hypoxia signaling to induce SOX2 expression, and co-treatment with DAPT and paclitaxel resulted in decreased viability of both CSC- and non-CSC populations in ovarian cancer cells." (PMID 27489349, 2016).
glioblastoma (101 papers, 2011 to 2026). The most malignant astrocytic tumor (WHO grade IV). "Mutation of NOTCH1 was found to be associated with a shorter progression-free survival and local relapse in glioblastoma." (PMID 40564017, 2025). "Non-EGFRvIII samples exhibited increased expression of S100A1, a marker of mesenchymal glioblastoma, whereas EGFRvIII samples exhibited higher expression of the classic/proneural subtype marker NOTCH1 and the proneural-associated gene IDH1." (PMID 38665799, 2024). "PIK3R1 and Notch1 mutations have been previously identified in patients with glioblastoma and low‐grade astrocytoma, correlating with shorter overall survival." (PMID 37667984, 2023). "At the protein level, we also analysed the expression of LIF, two known stem cell markers, Nestin and SOX2, as well as cleaved NOTCH1, the expression of which has been linked to glioblastoma proliferation and stemness." (PMID 35203105, 2022). "It is difficult to determine whether the astrocytoma cells originated from the Notch‐1 mutation, although Notch‐1 mutations are among driver mutations in all astrocytomas and glioblastomas, as well as normal tissues." (PMID 32069381, 2020). "Interestingly, protein expression analysis of NOTCH1 showed a significant difference between the five glioblastoma locations (p = 0.037) and was associated with RNA expression levels (p = 0.004)." (PMID 26637806, 2016). "In glioblastoma, NOTCH1 participates in mechanisms such as cell proliferation and increased vascularization." (PMID 40564017, 2025). "For example, glioblastoma-derived exosomes containing the Notch1 protein can induce carcinogenesis in normal glial cells through Notch1 signaling activation." (PMID 39766226, 2024). "One of the direct processes regulated by miR-34a in glioblastoma cells is considered to inhibit the expression of genes of the proteins Notch homolog 1 (Notch1) and Notch homolog 2 (Notch2), which act as transmembrane receptors." (PMID 36834933, 2023). "A previous study has indicated that Notch1 activation can trigger Wnt/β-catenin and NF-κB activation mediated by Akt phosphorylation, which enhances the invasive capabilities of glioblastoma." (PMID 37155149, 2023). "CRISPR/Cas9-mediated Notch1 knockout inhibits the proliferation and angiogenesis of glioblastoma multiforme cells." (PMID 36726958, 2022). "Atypical HIF-1α expression was associated with the Notch1 signaling pathway in both GBM and glioblastoma stem cells (GSC)." (PMID 36183290, 2022). "In the glioblastoma hypoxic microenvironment, the NOTCH1 pathway is activated by the target gene of hypoxia-inducible factor for the adaptation to low oxygen of tumor cells." (PMID 35897085, 2022). "Glioblastoma stem cells with downregulated NOTCH1 not only had a reduced self-renewal potential but were invasion-deficient in both the cell lines and mouse xenografts." (PMID 33430387, 2021). "In this review, we examined the contrasting activity of Notch1 and Notch2 and the signaling cascade that each generates in the angiogenesis of glioblastoma, the most invasive cancer of the central nervous system." (PMID 36643842, 2021). "All these studies demonstrate that the NOTCH1 pathway also regulates the GSC differentiation into endothelial cells in glioblastoma." (PMID 33946480, 2021). "In glioblastoma, Notch1 pathway is involved in tumorigenesis and maintenance, and as a consequence, inhibition of Notch1 led to decreased cell viability, proliferation and a more differentiated morphology." (PMID 33190170, 2021). "We previously reported that in glioblastomas, NOTCH1 pathway activation led to the upregulation of HEY1 and HEY2 transcription factors." (PMID 33925547, 2021).
glioblastoma (continued). "Confirming the control of GLS by Notch1, an independent study in glioblastoma cells reached similar conclusions, showing a decrease of intracellular glutamate after Notch1 blockade." (PMID 33314742, 2021). "In vitro, NOTCH1 downregulation inhibited proliferation of glioblastoma cells; in vivo, tumor bearing mice showed an improved survival when NOTCH1 was downregulated." (PMID 33579922, 2021). "In a study conducted on glioblastoma stem cells (GSCs), NOTCH1, SOX2, SALL2, POU3F and OLIG2 blocked differentiation in GSCs, confirming the observations made in GBM by Suvà and colleagues." (PMID 32634370, 2020). "Our work shows that one of the genes altered is LNX1, which increases the expression of Notch1, a gene important for glioblastoma progression." (PMID 33255632, 2020). "NOTCH1 downregulation has been shown to inhibit glioblastoma cell proliferation and neovascularization and to radiosensitize glioblastoma cell cultures and xenografts." (PMID 32604718, 2020). "Ectopic expression of miR-146a inhibits tumor development of a human glioblastoma cell line in an orthotropic xenograft model by downregulation of Notch1, which plays a key role in neural stem cell maintenance and is a direct target of miR-146a." (PMID 28435518, 2017). "Two recent mouse studies revealed an indispensable role of Rnd3 in mouse neuron development, and we have reported that Rnd3 regulated 293T and glioblastoma cell proliferation both in vitro and in vivo through Notch1 signaling." (PMID 29207629, 2017). "In glioblastoma cells were demonstrated that Notch-1 activation and p-53 restoration by resveratrol was correlated." (PMID 27834913, 2016). "In line with this, knockdown of DR5 using a DR5-specific siRNA oligonucleotide completely abrogated the sensitization of cells to TRAIL-mediated apoptosis upon Notch1 inhibition confirming DR5 as the main signal transducing TRAIL receptor in glioblastomas." (PMID 26469969, 2015). "A recent report indicated that Notch1 stimulation of glioblastoma stem cells resulted in the enhanced expression of ICAM-1." (PMID 26218064, 2015). "As a first step, we confirmed the sensitization of glioblastoma cells to TRAIL-induced apoptosis following Notch1 inhibition using long-term cell lines, primary cultures, and glioblastoma initiating cells." (PMID 26469969, 2015). "Here, we demonstrate that inhibition of the Notch1 signaling pathway sensitizes glioblastoma cell lines and glioblastoma initiating cells to apoptosis induced by the death ligand TRAIL." (PMID 26469969, 2015). "Considering the exceptional high apoptosis resistance of these cells, this finding is of particular interest and further emphasizes the eligibility of Notch1 as a therapeutic target for glioblastoma patients." (PMID 26469969, 2015). "We demonstrate that inhibition of Notch1 sensitizes glioblastoma cells to TRAIL-induced cell death by transcriptional upregulation of DR5 expression." (PMID 26469969, 2015). "The pathway of Notch1-mediated DR5 regulation described here is of particular importance for glioblastoma cell survival." (PMID 26469969, 2015). "To further confirm the relevance of DR5 upregulation after Notch1 knockdown for TRAIL-induced apoptosis in glioblastomas, we analyzed the extent of caspase-8 activation and DISC-formation following TRAIL-treatment." (PMID 26469969, 2015). "Moreover, upregulation of the NOTCH1 protein is seen in the clonal cells of glioblastoma, accentuating aggressive local tumor progression and distant relapse." (PMID 40564017, 2025). "KLF9 suppressed Notch-1 transcription in glioblastoma multiforme derived from neurospheres." (PMID 37308977, 2023). "In addition, resveratrol induced Notch-1 in glioblastoma cells while the Notch-1 inhibitor MRK-003 partially reversed the resveratrol-mediated inhibition of proliferation, supporting a tumor-suppressive role of Notch in glioblastoma." (PMID 35408894, 2022).
glioblastoma (continued). "The KLF9 is known to suppress Notch1 signaling and inhibit glioblastoma-initiating stem cells." (PMID 36231068, 2022). "Positive HEY1 and Notch1 expression was associated with shorter PFS and OS after chemo- and radiotherapy in patients with primary and recurrent glioblastoma, and Notch1 positive GSC had an increased potential to transform into endothelial cells possibly through Notch/VEGF crosstalk." (PMID 34680255, 2021). "Hence, the crosstalk between Smarcd1 and Notch1, which formed a feedback loop, was crucial in regulation of glioblastoma malignant phenotypes." (PMID 33190170, 2021). "Smarcd1 is an indispensable subunit of the SWI/SNF family, and we accordingly hypothesized that Smarcd1 restrained glioblastoma cell proliferation and invasion potentially by regulation of Notch1 pathway." (PMID 33190170, 2021). "Breaking up the malignant feedback loop between Smarcd1 and Notch1 may be a potential target in treating glioblastoma." (PMID 33190170, 2021). "However, treatment with Notch1 inhibitor DAPT restored the proliferation and migration abilities induced by low expression of Smarcd1, suggesting that downregulated Smarcd1 aggravated glioblastoma malignancy potentially via enabled Notch1 pathway." (PMID 33190170, 2021). "The molecular pathway alterations caused by the reduced ALPL in meningioma is still needed to be investigated further though a few studies uncover the association of ALPL and NOTCH1 regulation in human epithelial cells and ALPL is one of the key hub genes in glioblastoma." (PMID 33807688, 2021). "Moreover, they observed that NOTCH1 silence decreases the transition of CD133+ glioblastoma stem cells into endothelial progenitors." (PMID 33946480, 2021). "The crosstalk between Smarcd1 and Notch1 contributed to the malignancy of glioblastoma and break up of this feedback loop may be a potential therapeutic target for glioblastoma treatment." (PMID 33190170, 2021). "It is known that miR-34a can target NOTCH-1 in glioblastoma to suppress cancer growth." (PMID 32349744, 2020). "Considering the importance of Notch-1 signaling in glioblastoma development, Notch-1-antagonizing strategies may hold great promise for therapeutic approaches." (PMID 32998285, 2020). "Moreover, it was reported that upregulation of Notch1 was involved in the chemotherapy resistance and tumor recurrence in glioblastoma." (PMID 30622441, 2019). "The miR-34a targets Notch1 and Notch2 in glioblastoma and medulloblastoma." (PMID 28073349, 2017). "Additionally, increased Notch1 expression has been demonstrated in recurrent glioblastomas after chemo-radiation therapy and was identified as a prognostic marker for anti-angiogenic therapy." (PMID 26716508, 2016). "In summary, these results demonstrate that ATF6 may be involved in regulating NOTCH1 mRNA and protein expression, and that Notch1 may play a role in promoting proliferation of irradiated glioblastoma cells." (PMID 26716508, 2016). "Interestingly, by data mining in gene expression datasets, we found that—among other genes–PLXND1 levels were induced almost 4-fold upon constitutive Notch1 activation in glioblastoma stem cells." (PMID 27749937, 2016). "While additional work is needed to validate the mechanisms by which Notch1 may be involved in promoting cell survival downstream of ATF6, this investigation supports other studies identifying Notch1 as a key component in therapeutic resistance in glioblastoma." (PMID 26716508, 2016).